BRCA2 (BRCA2 DNA repair associated)
Diseases named in the same sentence as BRCA2 in open-access papers (continued):
Sharing a sentence is not in itself a finding about the gene and the disease.
ovarian carcinoma (continued). "According to a domestic study, the breast and ovarian cancer risks of BRCA1 mutation carriers up to the age of 70 were 72.1% and 24.6%, respectively, and 66.3% and 11.1%, respectively, in BRCA2 mutation carriers." (PMID 39590130, 2024). "Approximately 50% of patients diagnosed with ovarian cancer harbor tumors with mutations in BRCA1, BRCA2, or other genes involved in homologous recombination repair (HR)." (PMID 39408764, 2024). "Here, we use data from 572 families from Malaysia and Singapore with BRCA1 and BRCA2 PVs to estimate age-specific relative and absolute breast and ovarian cancer risks." (PMID 38333895, 2024). "The top 10 genes with most deleterious mutations in the Chinese ovarian cancer population were MC1R (12%), MLH1 (9%), PRKDC (8%), KIF1B (8%), FANCM (7%), FANCI (6%), PRSS1 (6%), SDHA (6%), BRCA2 (6%), and CFTR (5%)." (PMID 38817903, 2024). "When evaluating ovarian cancer risk by the age of 80 years for BRCA1 and BRCA2 carriers, the PRSHGS (22 SNPs predicting high-grade serous OC) at the 5th and 95th percentiles showed risks of 30% and 59%, and 10% and 28%, respectively." (PMID 38397209, 2024). "Women carrying these mutations face a significantly elevated risk of developing ovarian cancer, with percentages of 50% or more for BRCA1 and 20% for BRCA2." (PMID 39338246, 2024). "For ovarian cancer, the cumulative risks by age 80 years are 44% for BRCA1 mutation carriers and 17% for BRCA2 mutation carriers." (PMID 38717180, 2024). "One such approach is whole exome sequencing (WES), which can identify genetic variants associated with breast and ovarian cancer susceptibility beyond BRCA1 and BRCA2 mutations." (PMID 38660159, 2024). "We knocked down BRCA1 and BRCA2 in ovarian cancer cells and treated them with olaparib in the presence or absence of HMGA1‐knockdown." (PMID 39690136, 2024). "Germline variants were very rare and the only two genes with more than 2% prevalence in the patient cohort where BRCA1 and BRCA2, which was identified in ovarian cancer." (PMID 39277826, 2024). "The mean cumulative risk of having ovarian cancer with BRCA1 pathogenic mutation is 40% [95% confidence interval (CI): 35–46%], and 18% (95% CI: 13–23%) for patients carrying BRCA2 mutations." (PMID 38540206, 2024). "The lifetime risk of developing ovarian cancer (OC) is 39–44% for BRCA1 and up to 11–17% for BRCA2-mutated women, with an onset 5–10 years later." (PMID 36837501, 2023). "Targeted screening for high-risk groups: It is essential to design strategies that effectively target high-risk populations, such as individuals with a family history of ovarian cancer or known genetic predispositions, such as BRCA1 and BRCA2 mutations." (PMID 38084173, 2023). "Patients with ovarian cancer and TNBC are also more likely to have mutations in BRCA1 than BRCA2, while, the opposite is true for patients with ER + BC." (PMID 37589839, 2023). "Poly (ADP-ribose) polymerase (PARP) inhibitors has demonstrated in their effective management of BRCA1/BRCA2 mutant cancers, most notably in breast and ovarian cancers." (PMID 37190285, 2023).
ovarian carcinoma (continued). "Loss or inhibition of core c-NHEJ components, including DNA-PKcs, has been described as a mechanism of PARPi resistance in BRCA2-mutant ovarian cancer cells previously." (PMID 37143137, 2023). "Among Greek patients with breast and ovarian cancer, BRCA1 and BRCA2 LGRs alone comprise up to 24% of pathogenic variants identified in BRCA1 and BRCA2." (PMID 38067228, 2023). "For example, in the French-Canadian founder population, twenty variants in BRCA1, BRCA2, and PALB2 that predispose families to breast and ovarian cancer have been identified at increased frequencies." (PMID 36927983, 2023). "The three main genetic risk factors include a family history of breast or ovarian cancer, BRCA1 and BRCA2 mutations, and lynch syndrome." (PMID 36376606, 2023). "Since BRCA2 plays a role in hereditary ovarian cancer, several studies have been conducted on ways in which BRCA2 is involved in ovarian cancer." (PMID 37110218, 2023). "Ovarian cancer has been associated with penetrant germline pathogenic mutations in tumor suppressor genes, especially BRCA1 and BRCA2." (PMID 37958970, 2023). "It has been well-established that mutations in BRCA1 and BRCA2, compromising functions in DNA double-strand break repair (DSBR), confer hereditary breast and ovarian cancer risk." (PMID 37198153, 2023). "About 5–10% of all ovarian cancer cases are familial, and about 15–25% of hereditary ovarian cancer (HOC) cases are mediated by high-penetrance mutations in the BRCA1 and BRCA2 genes." (PMID 37013556, 2023). "Ultimately, our goal is to develop a highly specific test that can detect HGSOC, the deadliest form of ovarian cancer, at its earlier stages, especially in women who are at increased risk of developing ovarian cancer (e.g., BRCA1 and BRCA2 mutation carriers)." (PMID 37205573, 2023). "Mutations in the BRCA1, BRCA2, and MMR genes can increase the risk of ovarian cancer from 1.6% to 40%, 18%, and 10%, respectively." (PMID 37304283, 2023). "As for ovarian cancer, the estimated penetrance by age 70 was 48.3% (95% CI = 38.8% to 57.9%) for BRCA1 mutation carriers and 20.0% (95% CI = 13.3% to 29.0%) for BRCA2 mutation carriers." (PMID 37781206, 2023). "Genetic testing for hereditary breast and ovarian cancer revealed two pathogenic variants in the BRCA1 (c.5095C>T, p.(Arg1699Trp)) and in BRCA2 genes (c.658_659delGT, p.(Val220Ilefs*4)) in heterozygous form." (PMID 37895014, 2023). "The ARIEL 2 study evaluated the effectiveness of rucaparib in recurrent, platinum-sensitive, high-grade ovarian carcinoma with either BRCA1 and BRCA2 (BRCA) mutations or genomic loss of heterozygosity (LOH) scores." (PMID 37190285, 2023). "Likelihood ratios (LR) were calculated for the association of ovarian cancer histology and other characteristics, with BRCA1 and BRCA2 variant pathogenicity." (PMID 37076566, 2023). "On the other hand, a previous research demonstrated a higher prevalence of BRCA2 mutations compared to BRCA1 in other cancer types, including populations at increased risk for hereditary breast and ovarian cancer." (PMID 37804357, 2023). "Patients with ovarian cancer tended to have higher frequencies of BRCA1 and BRCA2 mutations, and the frequency of germline BRCA1 mutations (18/24, 75.00%) was higher than that of BRCA2 (11/19, 57.89%)." (PMID 37064128, 2023). "It is known that BRCA1 and BRCA2 are tumor suppressor genes involved in DNA repair, which are closely related to the incidence of ovarian cancer." (PMID 36611214, 2023). "According to the NCCN guideline, BRCA1, BRCA2, BRIP1, RAD51C and RAD51D have been proved with susceptibilities of ovarian cancer, and their deleterious mutation carriers were recommended for risk reducing salpingo-oophorectomy (RRSO)." (PMID 37386498, 2023). "The risks for breast (RR = 4.19, 95% CI = 3.53-4.98; P < 0.001) and ovarian cancers (RR = 4.65, 95% CI = 2.22-9.73; P = 0.001) in female relatives of BRCA2 carriers were also significantly higher than female relatives of non-carriers." (PMID 36861435, 2023).
ovarian carcinoma (continued). "Around 14% of epithelial ovarian cancers are due to BRCA1 and BRCA2 mutations, and about 65–85% of inherited ovarian tumors have resulted from a mutation in the BRCA germline." (PMID 36376606, 2023). "Mutations in breast- and ovarian-cancer-predisposing genes BRCA1 and, especially, BRCA2 are also associated with increased risk for pancreatic cancer development." (PMID 36975505, 2023). "BRIP1 is instead included on the corresponding gene panel for ovarian cancer predisposition, together with BRCA1, BRCA2, PALB2, RAD51C, RAD51D and the Lynch syndrome genes." (PMID 37563628, 2023). "About 5–10% of all ovarian cancer cases show familial clustering, and some 15–25% of familial ovarian cancer cases are mediated by high-penetrance mutations in the BRCA1 and BRCA2 genes." (PMID 37013556, 2023). "Meanwhile, about 20% of ovarian cancers are thought to be hereditary, and almost 32% are supposed to be caused by pathogenic mutations in the BRCA1 and BRCA2 genes." (PMID 36835955, 2023). "This reduces the risk of tubal/ovarian cancer by >96% if performed before the incidence rises (recommended age range: 35–40 years for BRCA1 and 40–45 years for BRCA2)." (PMID 37046756, 2023). "Of the 2005 BRCA1 and 1999 BRCA2 carriers, six and three cases of ovarian cancer were diagnosed, respectively, between 30 and 34 years." (PMID 36894311, 2023). "Approximately 20–30% of epithelial ovarian cancers occur in females with an inherited predisposition; most of these hereditary ovarian cancers are due to germline mutations in BRCA1 and BRCA2 genes." (PMID 37143950, 2023). "In breast and ovarian cancer tumors with a known mutation in HR genes, such as BRCA1 or BRCA2, a higher tumor mutational burden and a greater number of tumor-infiltrating lymphocytes have been observed; however, this outcome did not occur in our cohort." (PMID 37761329, 2023). "In this study, ovarian cancer histological subtypes were evaluated as predictors of BRCA1 and BRCA2 pathogenic variant status." (PMID 37076566, 2023). "In contrast to the general population, ovarian cancer in BRCA mutation carriers is diagnosed at an earlier median age (54 and 59.5 years for the BRCA1 and BRCA2 mutations, respectively, vs. 63 years for wild-type BRCA)." (PMID 36835955, 2023). "Borderline tumours, a separate entity of non-invasive epithelial ovarian cancers, are also characterised by a low frequency of BRCA1 and BRCA2 germline pathogenic variants." (PMID 37076566, 2023). "Other reported targets are HSP90 and VEGFR3 shown to attenuate RAD51, BRCA1, and BRCA2 expressions in ovarian cancer." (PMID 37370140, 2023). "To estimate the actual prevalence of pathogenic/likely pathogenic germline indels, we carried out a systematic analysis of BRCA1 and BRCA2 tumour sequencing data at homopolymeric stretches, in a cohort of consecutive high-grade ovarian cancer (HGOC) patients." (PMID 37179432, 2023). "The cumulative lifetime risk of ovarian cancer is 16–68% and 11–30% in female BRCA1 and BRCA2 gene alteration carriers, respectively." (PMID 37917945, 2023). "Women with BRCA1 and BRCA2 (BRCA1/2) pathogenic/likely pathogenic (P/LP) variants have a higher risk to develop breast and ovarian cancer." (PMID 36971799, 2023). "Several genes have been associated with increased risk of ovarian cancer, including BRCA1 and BRCA2, PALB2, BRIP1, RAD51C and RAD51D, with the largest percentage of cases (10-15%) being attributable to germline pathogenic variants in BRCA1 or BRCA2." (PMID 37076566, 2023). "Generally, carriers of BRCA1 and BRCA2 mutations have an increased risk (71.4-87% for the BRCA1 mutation and 77-88% for the BRCA2 mutation) of developing breast and ovarian cancers." (PMID 37719058, 2023). "Our findings indicated that female relatives of BRCA1 and BRCA2 carriers are at increased risks for breast and ovarian cancers." (PMID 36861435, 2023).
ovarian carcinoma (continued). "The primary outcome is the cumulative tubo-ovarian cancer incidence at the target age: 46 years for BRCA1 and 51 years for BRCA2 pathogenic variant carriers." (PMID 37045546, 2023). "For ovarian cancer (OC), the risk is around 40–50% for BRCA1 and 15–30% for BRCA2 mutation carriers." (PMID 38203374, 2023). "The lifetime risk of developing ovarian cancer is 40–45% for women with mutations in BRCA1 and 15–20% harboring BRCA2 mutations." (PMID 36305848, 2023). "The life-time risk for developing ovarian cancer in individuals harboring BRCA1 mutations is 39–48%, compared with 11–20% in those harboring BRCA2 mutations." (PMID 37664647, 2023). "•The ESMO guidelines state that all patients with high-grade ovarian cancer should be tested for BRCA1 and BRCA2 mutations (germline/somatic) at diagnosis." (PMID 37181681, 2023). "Ovarian cancer was the second and third most common cancer among female relatives of BRCA1 (21.95-fold increased risk) and BRCA2 carriers (4.65-fold increased risk), respectively." (PMID 36861435, 2023). "The increased risks of breast and ovarian cancer are linked to pathogenic variations (PVs) in BRCA1 and BRCA2." (PMID 37804357, 2023). "For tubal/ovarian cancer, the cumulative lifetime risk up to age 80 is 44% for BRCA1 GPV (95% CI: 36–53%) and 17% for BRCA2 GPV (95% CI: 11–25%)." (PMID 37046756, 2023). "Patients with inherited BRCA gene alterations have an increased risk of ovarian cancer, exceeding 5% in the early 40s for BRCA1 carriers and in the early 50s for BRCA2 carriers." (PMID 37917945, 2023). "Women who have inherited mutations in the BRCA1 or BRCA2 genes (BRCA-1/2) have substantially elevated lifetime risks for developing breast (80–90% lifetime risk) and/or ovarian cancer (18–40% lifetime risk)." (PMID 37365514, 2023). "RAD51C mutations have previously been reported to increase the risk for breast and ovarian cancer and to also be causative for a recessively inherited Fanconi anemia-like disorder, similar to BRCA1, BRCA2 and PALB2 mutations." (PMID 37578974, 2023). "This operation has been shown to lower the likelihood of developing ovarian cancer by 96% and the risk of breast cancer by 53% in individuals who have the BRCA1 or BRCA2 mutation." (PMID 37370973, 2023). "In cases other than HGSOC, BRCA2 alteration was detected in the only available RRS group tissue sample, and four PI3K pathway gene mutations were detected in other ovarian malignant tumor tissue samples." (PMID 36765826, 2023). "Loss-of-function mutation of a single allele confers a lifetime risk of ovarian cancer of 40% and 18% for BRCA1 and BRCA2, respectively." (PMID 35159349, 2022). "This is an urgent need especially in the subset of patients at high-risk of ovarian cancer due to inherited BRCA1 and BRCA2 mutations." (PMID 36311816, 2022). "Breast and ovarian cancer risks differ depending on the position and the type of BRCA1 and BRCA2 mutations." (PMID 36010882, 2022). "In brief, in ovarian cancer cells, Olaparib increased ALDH1A1 expression through the BET protein BRD4, thereby activating alternate DNA repair pathways in cells harboring a BRCA2 mutation." (PMID 35205643, 2022). "Immunohistochemical staining was quantitated on tumor microarrays of human tumor samples obtained from 357 patients with epithelial ovarian cancer to ascertain BRCA2 expression levels." (PMID 36230652, 2022). "In a cohort of 8,162 breast/ovarian cancer families from the German Consortium for Hereditary Breast and Ovarian Cancer, eight female DH patients for BRCA1 and BRCA2 mutations were described and analyzed for their phenotypic features." (PMID 36003761, 2022). "Considering its high performance and accuracy in the classification of variants in BRCA1 and BRCA2, we believe that it could provide sufficient evidence for the localization of pathogenicity in these specific genes and thus contribute to the prognosis and/or diagnosis of breast or ovarian cancer." (PMID 36358902, 2022).
ovarian carcinoma (continued). "Along with successful validation on patients carrying BRCA1 and BRCA2 mutations, positive effects of PARPi were also observed in patients without BRCA mutations with high-grade serous or poorly differentiated ovarian carcinoma or TNBC." (PMID 36499000, 2022). "The clinical utility of germline genetic testing for BRCA1 and BRCA2 has been established in patients with histories suggestive of hereditary breast and ovarian cancer." (PMID 35626031, 2022). "The enzymatic inhibition of DNA repair PARPs by small molecules has pioneered a synthetically lethal target therapy strategy for treatment of tumours characterised by DDR defects, such as breast and ovarian cancer carrying BRCA1 and BRCA2 mutations." (PMID 35964058, 2022). "For epithelial ovarian cancer patients who received chemotherapy, we confirmed survival benefit for BRCA1 and BRCA2 germline pathogenic variant carriers." (PMID 36137114, 2022). "Our work extends these observations by showing that the expression of BRCA1 and BRCA2 genes significantly correlates with that of an additional 12 HR genes in clinical ovarian cancer samples." (PMID 35203410, 2022). "Such approaches have been shown to be efficacious in treatment of breast and ovarian cancers of BRCA1/2 carriers, as well pancreatic cancers with an inactivation of BRCA1, BRCA2, or PALB2 and an HR deficiency tumor mutation signature." (PMID 36497436, 2022). "Approximately 20–30% of EOC occurs in females with an inherited predisposition; most of these hereditary ovarian cancers are due to germline mutations in BRCA1 and BRCA2 genes." (PMID 35805770, 2022). "In unselected ovarian cancer patients, BRCA1 pathogenic variants were more common compared to BRCA2 (20.07% vs. 6.19%)." (PMID 36439508, 2022). "Risk management of further cancers was not described in the three published reports of BRCA1 mosaicism or the report of BRCA2 mosaicism in ovarian cancer." (PMID 36068545, 2022). "The majority (91.4%) of patients had high-grade serous histology, and the population reflected typical ovarian cancer demographics, with a mean age of 65 years and 17% BRCA1/BRCA2 mutation carriers." (PMID 35972817, 2022). "BRCA1- and BRCA2-associated Hereditary Breast and Ovarian Cancer Syndrome (HBOC) increases the relative and absolute risk of developing breast and ovarian cancer and, to a lesser extent, prostate and pancreatic cancer." (PMID 35395021, 2022). "Inherited germline mutations in the breast cancer gene 1 (BRCA1) or BRCA2 genes (herein BRCA1/2) greatly increase the risk of breast and ovarian cancer, presumably by elevating somatic mutational errors as a consequence of deficient DNA repair." (PMID 35025760, 2022). "Their paper reported that among patients with invasive epithelial ovarian cancer, having a germline mutation in BRCA1/2 was associated with improved 5‐year overall survival and that BRCA2 showed the best prognosis." (PMID 35608067, 2022). "The clinical utility of positive findings in DNA damage-repair (DDR) genes BRCA1 and BRCA2 for the treatment of patients with breast or ovarian cancer is well established." (PMID 35626031, 2022). "Our patient cohort aligned with the expected demographics in epithelial ovarian cancer (largely high-grade serous histology, average age of 65 years, and 17% BRCA1/BRCA2 mutation rate) but was more heavily pretreated than that in the OCEANS trial cohort." (PMID 35972817, 2022). "Meanwhile, due to its specific genetic background, more than 15% of ovarian carcinoma patients carry germline mutations, and an additional 5–11% of patients carry somatic mutations in either the BRCA1 or BRCA2 gene." (PMID 35887672, 2022). "Approximately 5% to 10% of ovarian cancers are due to inherited germline mutations of susceptible genes, and about 90% of such cases involve mutations of BRCA1 or BRCA2 genes." (PMID 35180738, 2022).